RELA (RELA proto-oncogene, NF-kB subunit)
Diseases named in the same sentence as RELA in open-access papers (continued):
Sharing a sentence is not in itself a finding about the gene and the disease.
cancer (continued). "Consequently, we should see earlier onset of tumourigenesis or reduced survival in cancer models where RelA plays a role." (PMID 36240065, 2022). "However, the mechanistic details of how redox signaling regulates RelA-driven cellular proinflammatory events that drive therapy resistance or exploiting these events in cancer treatment remain to be investigated." (PMID 35402225, 2022). "RELA is a well-known master transcription factor in the NF-κB pathway, which is intimately involved in various pathophysiological processes such as inflammation and cancer." (PMID 33685520, 2021). "RELA phosphorylation resulted in cancer progression by regulating NF-κB signaling." (PMID 34321012, 2021). "To further confirm our results that the effects of p65KD on the expression of the epithelial cell phenotype were mediated through CD82, we knocked-down the expression of CD82 in RelA/p65KD A549 cancer cells using the control retroviral vector pSIREN-ZsGreen or pSIREN-ZsGreen-shCD82." (PMID 34503110, 2021). "RelA is a subunit of NF-κB involved in metastasis, especially cancer cell migration and invasion." (PMID 34445799, 2021). "RELA is one of the transcription factor genes in the NF-κB signaling pathway that contributes to human disease processes, notably inflammatory diseases and cancer." (PMID 34349833, 2021). "RelA-specific inhibitors may contribute not only to research tools for NF-κB but also for cancer treatment." (PMID 33266352, 2020). "In addition to well-documented RelA-based canonical NF-κB pathway in cancer development, the present study demonstrates that the RelB-based noncanonical NF-κB pathway plays a crucial role in advanced BCa as followed by ER functional decline." (PMID 32807176, 2020). "Moreover, it suggested that RelA made a significant contribution to cancer cell migration and invasion by suppressing the expression of cell adhesion factors like ICAM." (PMID 31952106, 2020). "RelA (in the NF-κB pathway) and β-catenin (in the Wnt/β-catenin pathway) are repressors of E-cadherin expression and are required for the migration and invasion of cancer cells." (PMID 31222140, 2019). "RelA, p50 and IκBα have all been reported to reside within the mitochondria of cancer cell lines as well as in tissues, suggesting that some NF-κB effects on mitochondria might be direct." (PMID 31484794, 2019). "A recent study by Dikstein and colleagues reported that Withaferin A (WFA), a naturally occurring anti-inflammatory and anti-cancer phytochemical, disrupts RelA dimerization by interacting with a conserved hydrophobic core domain and dimerization scaffold within RelA and other NF-κB subunits." (PMID 31787981, 2019). "Our novel findings also showed that BAY 11‐7082 suppressed the acidic bile‐induced miR‐192 levels in treated human hypopharyngeal cells with strong positive correlations between BAY 11‐7082‐induced miR‐192 levels and inflammatory and key cancer molecules, such as RELA(p65), STAT3 and TNF‐α." (PMID 29516639, 2018). "Furthermore, based on the Pearson correlation analysis of TCGA Pan-Cancer, Notch1 expression was positively correlated with RELA (NF-κB(p65)) expression in GBM." (PMID 29410396, 2018). "Interestingly, NEMO (IKBKγ) (FC 1.11), IKBKB (FC 0.94), NFκB1 (FC 0.92) and RELA (FC 1.12) were only slightly changed in carcinoma tissue compared to normal mucosa." (PMID 29188362, 2018). "Interestingly, IL-6 is known to activate STAT3 which in turn interacts with NF-κB to form ReLA survival complex that gives the radio resistant property to cancer cells." (PMID 29070894, 2017).
cancer (continued). "CRM1 is known to export RelA from the nucleus, a mechanism that could explain the observed cytoplasmic localization of RelA in our samples and that could render RelB the only nuclear NF-κB transactivator in laryngeal and other cancers." (PMID 29371965, 2017). "Interestingly, overexpression of PKM2 in cancer cells with abrogated p65/RelA had a minimal effect on HIF promoter activity." (PMID 26739387, 2016). "Some of these cancers with evidence of NF-kB activation expressed abundant RelA, which was present in both the nucleus and cytoplasm (nPcH); these cancers may possess an active NF-kB pathway stimulated by paracrine or autocrine factors." (PMID 26460486, 2015). "Although previous reports from various human cancers support a predominantly canonical NF-κB activation pathway mostly mediated by RelA/P50, recent data along with ours highlight the possibility for a non canonical NF-κB activation pattern in different cancers." (PMID 26147201, 2015). "A practical consequence of our study is the suggestion that strategies to induce RelA or IRF1 activity may also be useful in patients with Rb-competent cancers." (PMID 26460486, 2015). "However, a number of ER+ cancers did harbor nuclear RelA (12 of 55, or 22%) in the Boston cohort of tumors." (PMID 26460486, 2015). "Such a set of hubs contained important transcription factors such as MYC and E2F1 and oncogenes such as JUN and RELA and was enriched with genes that appeared in cancer pathways (p<2.2×10−8), the cell cycle (p<3.5×10−6) and several important signaling pathways from DAVID." (PMID 21390271, 2011). "However, information on the expression of RelA/p65, the major transcription activating NF-κB subunit, in these carcinomas and possible correlations thereof with NF-κB activation and patient survival is not available." (PMID 17622249, 2007). "Importantly, although all subunit combinations were observed in cancer cores, the canonical RelA–p50 pair was less frequently detected than other subunit pairs." (PMID 16205698, 2005). "It has been shown that constitutively nuclear and active RelA/p50 dimers can prevent cell death by apoptosis in many cancer cell types after chemotherapy, radiotherapy, or TNF-α treatment and have also been detected in the nuclei of pancreatic and breast carcinomas." (PMID 16205698, 2005). "Conflicting reports of whether TNFα-induced RELA translocation is cell cycle regulated may be due to cancer cell type-specific deregulation of cell cycle proteins or RELA may not physically interact with E2F1 in PDAC cells in general or specifically in unsynchronised cells." (PMID 39110005, 2024). "The establishment of the HDACs-IKKα-RelA/p65 axis provides better understanding of molecular pathways through which deacetylases regulate transcriptional activity, which may facilitate the development of more effective cancer therapies." (PMID 35188360, 2022). "In addition, BBR could inhibit MDA-MB-231 cells as an agonist of GPER1 by inhibiting the nuclear translocation of RELA, which indicated NF-κB inhibition and anti-cancer effects." (PMID 34768896, 2021). "There are 10 highly significant, direct and physical associators with a confidence score of ≥5.0 namely – RELA, HMOX2, EZH2, p-10Y-ERBB3-1, WDR1, ERRFI1, PRG2, FMR1, DEFA6-(?-100), cytf_human and the majority of the network associators of POTEE are epigenetically activated in many cancers." (PMID 34788504, 2021). "However, the mRNA expression levels of p65/RelA were similar between cancer and normal tissues, suggesting the differences in protein expression of p65/RelA between cancer and normal tissues seemed to be due to the protein stability or translational efficiency of p65/RelA." (PMID 31580526, 2019). "Because metagenes encoding components of the shape-gene network are predictive of clinical outcomes and of the central position of RELA/NF-κB within this network, we reasoned that NF-κB activity may play a role in cancer progression in response to the actions of this network." (PMID 27864353, 2017).
cancer (continued). "Key targets such as TNF, PTGS2, PRKACA, HSP90AB1, RELA, and NFKBIA appeared to be involved in chemical carcinogenesis–receptor activation, pathways in cancer, IL-17 signaling pathway, cholinergic synapse pathway, and regulation of lipolysis in adipocytes." (PMID 39064924, 2024). "Functional pathway of “Molecular Mechanism of Cancer” was indirectly influenced by activated NFKBIA, bone morphogenetic protein 10 (BMP10), RB transcriptional corepressor like 2 (RBL2) and RELA." (PMID 39342193, 2024). "A cancer cell line study demonstrated that C4BPA was expressed intracellularly in cancer cells and interacts with the NF-κB family member RelA and regulates apoptosis." (PMID 37817005, 2024). "Using a series of cancer tissues from HAGC patients, we observed a concomitant increase of nuclear localized RelA with high α-Actinin-2 levels." (PMID 37337244, 2023). "In these cancer models, ERK5 activity induces p65/RELA nuclear translocation and transcriptional activity, whereas ERK5 inhibition or silencing impairs p65/RELA activity." (PMID 36123565, 2022). "In this study, we screened transcription factors and found that RELA (p65), a subunit of nuclear factor kappaB (NF-κB), is critical for CD271 transcription in cancer cells." (PMID 36273237, 2022). "Since the RelA T505 residue can be phosphorylated by the checkpoint kinase CHK1, we next determined whether the RelA T505A mutation would also affect cell survival in response to treatment with CHK1 inhibitors, an important class of novel cancer therapeutics currently in clinical trials." (PMID 36240065, 2022). "In cancer development, BRD4 linkage to NF-κB prevents RELA ubiquitylation, which then blocks RELA degradation through proteasome." (PMID 35401196, 2022). "Except for CDKN1B and RELA, the expression levels of CASP7, CDH3, EIF4G1, and EIF4EBP1 were increased significantly in most individual cancer stages compared with normal samples." (PMID 35787690, 2022). "The Cancer Proteome Atlas (TCPA) created a Kaplan Meier (KM) plot for miR-520c-3p targets AKT1, AKT2, AKT3, MTOR, NF-κB (RelA), PDK1, PI3K, and PTEN." (PMID 35634241, 2022). "Most of the activated TFs are involved in cancer progression through the TIME, such as the NFκB family (NFKB1, NFKBIA, and RELA) and the STAT family (STAT1, STAT2, and STAT6), which are critical in M1 and M2 macrophage polarization." (PMID 36230879, 2022). "Surprisingly, BCL2L1, E2F1, HRAS, MAPK8, MITF, RELA, and SP1 were all found in the mitophagy and cancer pathways." (PMID 34262589, 2021). "Several known potent oncogenes that regulate CDKN2B-AS1 expression in various cancers have been reported in the literature, including MYC, RELA, and ERBB2." (PMID 33849428, 2021). "By trans-element analysis from the set of altered enhancers, we successfully identified IRF2, RELA, NFATC2, etc., as essential TFs involved in cancer cell growth and migration, possibly via establishing oncogenic enhancer programs." (PMID 34294701, 2021). "RelA is highly expressed in PDAC patients and has been shown to be involved in the malignant transformation of cancer." (PMID 33266352, 2020). "In cancer cells, the BRD4/RelA complex avoids degradation, resulting in continuous activation of NFκB, which promotes cell proliferation." (PMID 33348732, 2020).
cancer (continued). "The key targets of GTF for cancer-related pain were Jun proto-oncogene (JUN), mitogen-activated protein kinase 1 (MAPK1), and RELA proto-oncogene (RELA)." (PMID 33224254, 2020). "In cancer cells, mitochondrial ROS produced after low-power laser irradiation have been shown to upregulate BECN1 expression via the rise of p65/RELA transcriptional activity." (PMID 31781334, 2019). "We believe that these knowledge and new combination therapies are applicable to many other cancer types, particularly given that PDLIM2 repression and RelA and STAT3 activation are common in human cancers." (PMID 31757943, 2019). "Studies in cancer have found that NF-κB is regulated by BRD4, acting as a coactivator, by binding to acetylated lysine-310 residue of the RelA NF-κB subunit." (PMID 31780938, 2019). "To find a possible link between these three cancers subjected to arsenicals exposure, we merged the three networks and identified seven HUB nodes (RXRA, MAP3K7, NR3C1, PABPC1, NDRG1, RELA and CTNNB1) of the linking region between three cancer networks." (PMID 29991691, 2018). "To provide an overview on the occurrences of distinct NF-κB subunits in cancer subtypes, we assessed the overexpression of the NF-κB subunits RELA, RELB, and c-REL in human cancers by database mining, using COSMIC." (PMID 29673141, 2018). "This shows that genes containing conserved RELA, STATI, IRFI, NF-kappaB, PEND, HLF, REL, CEBPA, DI_2, and NFKB1 binding sites are indeed over-represented in cancer-related DEGs and this over-representation can be recuperated computationally." (PMID 29593668, 2018). "RELA (NFκB) is known to be constitutively active in many cancers where it up-regulates anti-apoptotic and other oncogenic genes and here we observe a direct interaction between STAT3 and RELA." (PMID 30143675, 2018). "Here, we show that activation of EGFR in human cancer cells results in PKCε-dependent MIIP phosphorylation and its interaction with RelA in the nucleus." (PMID 29038521, 2017). "Suppression of RELA, NFKB1 and NEMO inhibited “circular chemo-repellent induced defects” (CCIDs), which form when cancer cells cross the lymphatic vasculature, by ~20–30%." (PMID 26513020, 2015). "NF-κB/RELA and STAT3 potentially partner in transcriptional regulation of tumorigenic genes in cancer cells." (PMID 26046794, 2015). "Finally, we show by immunohistochemistry (IHC) that RelA/p65 is abundantly expressed in malignant cells that aberrantly express hTREX84 indicating that RelA/p65 might play a pivotal role in regulating hTREX84 expression in cancer." (PMID 22952718, 2012). "• Exertion of anticancer effects through 3 major pathways: apoptosis (BIRC3, BIRC5, caspase-8, caspase-9, and PARP1), transcriptional dysregulation in cancer (CDKN1A, CDKN1B, MMP9, MYC, JUN, and RELA), and cancer progression (caspase-3, CCND1, CTNNB1, VEGFA, and Wnt-1)." (PMID 39181121, 2025). "While the transcriptional interaction between RELA and STAT3 has been examined in the context of cancer, it is unclear whether this same mode of regulation exists in the context of macrophage-mediated inflammation during wound healing." (PMID 39435663, 2024). "Moreover, RNF126 showed a positive correlation with both RelA and AKT at the mRNA level in most cancer and normal tissues through correlation analysis of The Cancer Genome Atlas (TCGA) database and The Genotype‐Tissue Expression (GTEx) database, respectively." (PMID 36563124, 2023). "When comparing the candidates to the non-candidate genes (those non-NFκB/TNF hallmark genes receiving no votes across all cancer types), the candidates displayed higher similarity to the canonical pathway genes TNF, RELA, NFKB1, and RELB." (PMID 37475016, 2023).
cancer (continued). "We assessed the predictive significance of NF-κB p65 (RelA) and TNFα in cancer using GEPIA to determine whether the expression levels of these proteins are connected to the prognosis of cancer patients." (PMID 37892820, 2023). "In the Hong Kong cohort, NFKB1/RELA and PIEZO1 expression in identical samples were assessed through IHC, and their protein levels showcased a direct correlation when scoring the positive cancer cell percentage (n = 128)." (PMID 37983931, 2023). "Given that PolI silencing induces NF-κB (RelA) displacement to the nucleolus, the PolI inhibitor BMH-21 may be used to sensitize cancer cells to apoptosis." (PMID 35620053, 2022). "As shown, the expression of NFKB1, NFKB2, REL, RELA, and RELB varied in different cancer types." (PMID 35036435, 2022). "Binding motifs for many essential TFs, such as RXRA, NFE2L2, ESRRA, IRF2, RELA, ESRRA, SOX2, and SMAD2/3, key TFs that mediate TGFβ signaling in epithelial-mesenchymal transition (EMT) and cancer metastasis, were enriched in common gained or LNC-specific gained enhancers, with some overlapping TFs." (PMID 34294701, 2021). "The three clusters generated contained genes or proteins involved in apoptosis (BIRC3, BIRC5, PARP1, CASP8, and CASP9), transcriptional dysregulation in cancer (CDKN1B, RELA, CDKN1A, MYC, JUN, and MMP9), and cancer progression (CCND1, CASP3, CTNNB1, WNT1, and VEGFA) pathways." (PMID 34836311, 2021). "Notably, BCL2L1, E2F1, HRAS, MAPK8, MITF, RELA, and SP1 were found in both mitophagy and cancer pathways." (PMID 34262589, 2021). "In other words, suppression of RelA did not directly kill cancer cells, but suppressed metastasis/invasion." (PMID 31952106, 2020). "Hence, we show that RelA expression can reduce cancer metastasis, and MPEG-PCL-CH2R4H2C is an effective siRNA carrier for anti-metastasis cancer therapies." (PMID 31952106, 2020). "Various members of the NF-κB family are constitutively activated in many cancers via one of the two pathways: the canonical pathway involving RelA, NF-κB1 p50 and c-Rel and the non-canonical pathway engaging RelB and NF-κB2 p52." (PMID 32122395, 2020). "The binding of RelA with BDR4 blocks its ubiquitination and inhibits its subsequent proteasome-mediated degradation, leading to the excessive activation of NF-κB and aberrant proliferation of cancer cells." (PMID 33574760, 2020). "In cancer cells, the binding of BDR4 to RelA/NF-κB subunit blocks RelA ubiquitinilation and its subsequent proteasome-mediated degradation, leading to sustained nuclear NF-κB activation and, therefore, showing a mechanisms involved in aberrant cell proliferation." (PMID 31780938, 2019). "The knockdown of MSK1/2 did not affect the transforming activity provoked by Ras (G12V), suggesting that MSK1/2‐p65/RelA signaling axis does not contribute to cancer initiation." (PMID 31580526, 2019). "While not studied in cancer, it was reported that IKKε can phosphorylate RelA at Ser468 to promote transactivation potential." (PMID 30223576, 2018). "While much of the NF-κB-related research focuses on IKKβ/RelA, the noncanonical NF-κB pathway has proven to be equally critical in cancer and other diseases." (PMID 29874793, 2018).